NFATC4 (nuclear factor of activated T cells 4)
Diseases named in the same sentence as NFATC4 in open-access papers (continued):
Sharing a sentence is not in itself a finding about the gene and the disease.
prediabetes (1 paper, 2024). "It was found that higher levels of inflammatory markers (IL-18, TNF-α, IL-6) and increased NFATC4 gene expression were associated with a greater risk of prediabetes compared to healthy controls." (PMID 40027364, 2024). "By examining these markers in prediabetic individuals compared to controls, we seek to uncover the role of NFATC4 in inflammation associated with prediabetes." (PMID 40027364, 2024). "The study aims to examine the relationship between physiological, demographic, anthropometric, lifestyle factors, inflammatory markers, and NFATC4 gene expression in prediabetes." (PMID 40027364, 2024). "This case-control study aims to investigate the association between physiological, demographic, anthropometric, lifestyle factors, inflammatory markers and NFATC4 gene expression, in the context of prediabetes." (PMID 40027364, 2024). "Receiver operating characteristic (ROC) curve analysis identified IL-18 and NFATC4 as the most promising biomarkers for predicting prediabetes, followed by TNF-α and IL-6." (PMID 40027364, 2024). "Despite the known role of inflammation in glucose homeostasis, the involvement of the Nuclear Factor of Activated T Cells 4 (NFATC4) gene in prediabetes remains underexplored." (PMID 40027364, 2024). "The combination of elevated inflammatory markers, NFATC4 expression, and lifestyle factors like SES and alcohol consumption provides a comprehensive view of prediabetes risk." (PMID 40027364, 2024). "Elevated levels of IL-18, NFATC4, TNF-α, and IL-6 were all associated with significantly higher odds of prediabetes compared to healthy controls (all P < 0.001)." (PMID 40027364, 2024). "ROC curve analysis evaluated the predictive ability of four inflammatory markers-IL-18, TNF-α, IL-6, and NFATC4-for classifying prediabetes cases and controls." (PMID 40027364, 2024). "Understanding the relationship between inflammatory markers and NFATC4 gene expression in prediabetes could provide crucial insights into disease mechanisms and potential therapeutic targets." (PMID 40027364, 2024). "Multivariate regression analysis further identified socioeconomic status (SES), IL-18, NFATC4, TSH, triglycerides, and HDL as independent predictors of prediabetes." (PMID 40027364, 2024).
pulmonary hypertension (1 paper, 2022). Increased pressure within the pulmonary circulation due to lung or heart disorder. "The activation of NFATC3 and NFATC4 by hypoxia is associated with pulmonary hypertension due to the thickening and stiffening of pulmonary arteries." (PMID 36077479, 2022).
retinal degeneration (1 paper, 2024). Degeneration of the retina. "The research on NFAT transcription factors in RGC survival and regeneration following injury has been largely discontinued since 2014 when Xu and colleagues demonstrated an overlapping pattern of NFATc4, cleaved caspase-3, and FasL in a light-induced model of retinal degeneration." (PMID 38639863, 2024).
schwannoma (1 paper, 2022). A benign, usually encapsulated slow growing tumor composed of Schwann cells. "In Schwannoma, NFATc4 and SOX10 synergistically enhanced KROX20 activity and induced P0 transcription to regulate the cell proliferation." (PMID 35698138, 2022). "When overexpressing SOX10 in Merlin-null Schwannoma cells in which the SOX10 level was reduced to restore Merlin tumor suppressor, NFATc4 was activated with nuclear translocation and the cell growth was alleviated." (PMID 35698138, 2022).
Splenomegaly (1 paper, 2022). Abnormal increased size of the spleen. "It is unlikely that gene knockdown of NFATc4 by AAV in the mPFC can affect LPS-induced splenomegaly in mice." (PMID 35064103, 2022). "We further studied the impact of NFATc4 knockdown on LPS-induced depression-like phenotype, splenomegaly, and increased plasma inflammatory cytokines." (PMID 35064103, 2022). "In contrast, NFATc4 knockdown in the mPFC did not affect body weight loss and splenomegaly in the LPS-treated mice." (PMID 35064103, 2022). "Thus, it seems that other mechanisms except NFATc4 may play a role in the effects of (R)-ketamine on the LPS-induced splenomegaly." (PMID 35064103, 2022).
tongue cancer (1 paper, 2021). A malignant neoplasm affecting the tongue.
tumor (23 papers, 2015 to 2024). "Inducible activation of NFATC4 also resulted in the effective suppression of MYC expression in tumor cells." (PMID 38418814, 2024). "According to recent decade of researches, NFATc4 protein has been recognized as an important transcription factor during the tumor initiation, cell growth, migration, invasion, metastasis, and drug resistance." (PMID 35698138, 2022). "In these tumors, NFATC4 participates in cancer progression through promoting tumor cell proliferation or chemotherapy resistance, while we inferred that it regulates immune responses in the progression of AML." (PMID 33329712, 2020). "On the other hand, NFATc2 and NFATc4 expression was comparable between normal and tumour samples, although with low abundance." (PMID 31249342, 2019). "The expression of the NFATC4 protein controlled the cloning efficiency and radiosensitivity of A549 and FaDu tumor cells." (PMID 29253018, 2017). "NFATc4 could also play an important role in tumor immune microenvironment through EVs from NFATc4-expressing cells." (PMID 35698138, 2022). "NFATc4 could promote tumor formation through CXCR4 expression up-regulation whereas NFATc4 inhibited cell proliferation by down-regulating MYC during cisplatin resistance-associated quiescence." (PMID 35698138, 2022). "Furthermore, NFATc4 was related to the tumor immune microenvironment through recruiting macrophage and Tregs." (PMID 35698138, 2022). "It is also reported that NFATc4 could take part in cell growth, cell migration, tumor metastasis, and patient survival recently." (PMID 35698138, 2022). "However, in other types of malignancies, other isoforms (e.g. NFATc2) were also shown to contribute to the promotion of tumor progression, while inhibitory functions of NFATc2 and NFATc4 were noted." (PMID 25638160, 2015). "NFATc4 may perform a dual-function during tumor progression like other NFAT proteins." (PMID 35698138, 2022). "In tumor tissue, we observed a higher expression of NFAT factors and in particular an increased activation and nuclear migration of NFATc4 on RCC tumor tissues belonging to patients that developed metastases when compared to those who did not." (PMID 34445576, 2021). "NFATC1, NFATC2, NFATC3, NFATC4, and NFAT5 were all highly expressed in the tumor tissue of the TCGA dataset compared with normal tissue of the GTEx dataset." (PMID 31827081, 2019). "NFATC4 regulates HIF-1A/VEGF signaling and acts as a transcription factor that regulates cell survival, differentiation, angiogenesis, invasive migration, and the tumor microenvironment." (PMID 29253018, 2017). "We first examined messenger RNA (mRNA) expression of NFAT family members (NFATc1, NFATc2, NFATc3, NFATc4, and NFAT5) in 30 pairs of HCC tumor tissues (T) and corresponding adjacent nontumor tissues (NT) by qRT‐PCR." (PMID 30085405, 2018).
cancer (22 papers, 2015 to 2025). A tumor composed of atypical neoplastic, often pleomorphic cells that invade other tissues. "The same intron retention event in the NFATC4 gene we identified in our study has been implicated in prognosis in other cancer types." (PMID 37924098, 2023). "It has been reported that NFAT family including NFATc1, NFATc2, NFATc3, and NFATc4 were closely associated with many kinds of cancers." (PMID 31823518, 2020). "Wnt pathway, which is known to regulate transcription activity and cause aberrant cell division and migration associated with cancer formation, was found indeed deregulated as documented by the downregulation of Wnt2, Nfatc1, and Nfatc4 genes." (PMID 26559525, 2015). "NFATC4, an oncogene located on chromosome 14, encodes a protein from the nuclear factor of an activated T-cell family, which is a DNA-binding complex, is expressed in many cancer tissues, and has been shown to enhance tumorigenesis." (PMID 35629083, 2022). "Another TF, NFATC4, has been reported to be aberrantly activated and is involved in initiation, proliferation, invasion, and metastasis in several types of cancer." (PMID 39273015, 2024). "NFATC4-positive cancer cells were characterized by decreased proliferation, G0 cell cycle arrest, reduced cell size, and chemotherapy resistance in vitro and in vivo." (PMID 38418814, 2024). "Treatment of cancer cells with cisplatin resulted in NFATC4 nuclear translocation and activation of the NFATC4 pathway, initiating a program of cellular dormancy." (PMID 38418814, 2024). "Taken together, growing evidences revealed the molecular regulatory mechanism of NFATc4 and its crucial role in the cancer development." (PMID 35698138, 2022). "In TCGA and GTEx database, 16 types of cancer show lower mRNA levels of NFATc4 when comparing with normal tissues, while 3 types of cancer show higher mRNA levels." (PMID 35698138, 2022). "NFATc4 also provided as a novel potential molecular target for cancer therapies, since NFATc4 participated in cell proliferation, migration, invasion, colony formation, 3D spheroid formation, and cell apoptosis." (PMID 35698138, 2022). "In this review, we would like to discuss the recent knowledge on the expression, PTM and epigenetic regulations of NFATc4, its interaction partners and downstream components, as well as its biological function in cancers and other diseases." (PMID 35698138, 2022). "All in all, the result from these studies strongly suggest that NFATc4 has the potential as a molecular therapeutic target in multiple human cancer types." (PMID 35698138, 2022). "Since the activated NFATc4 has been detected in the precancerous lesions and cancers, its downstream genes are noteworthy to be elucidated." (PMID 35698138, 2022). "Yet, there are only a few researches cover the protein level of NFATc4 in cancer and normal tissues." (PMID 35698138, 2022). "The upregulated expression of Nucleolin, Prkcsh, Prkar2b, and Zbed3 and the downregulated expression of Nfatc4 promoted cancer cell proliferation, migration, and invasion by activating the Wnt/β-Catenin signaling pathway." (PMID 34848840, 2021). "PPP3CA is reported to interact with NFATs (NFATc1, NFATc2, NFATc3 and NFATc4) transcriptional factors, and have a crucial role in the regulation of immune response, and invasiveness of cancer cells." (PMID 28881575, 2017). "Recent discoveries, such as NFATc1 pro-angiogenic effect in retinal microvascular endothelial cells, the association of NFATc3 and NFATc4 with immune-related diseases, and the significant contributions of NFAT proteins to cancer progression, highlight the importance of these molecules and pathways." (PMID 39822413, 2024). "NFATc4 is a critical factor in many cancers, such as the AML prognosis." (PMID 39822413, 2024). "Furthermore, we perform database analysis to reveal the prognostic value of NFATc4 in various cancers and discuss the current unexplored areas of NFATc4 research." (PMID 35698138, 2022).
cancer (continued). "Thus, there are compelling reasons to believe that it is necessary to further study the unrevealed mechanisms of NFATc4 in cancer." (PMID 35698138, 2022). "In ovarian quiescent cancer stem-like cells (CSCs), NFATc4 is also overexpressed." (PMID 35698138, 2022). "NFATc4 may be considered as a new target to prevent the malignant cancer progression." (PMID 35698138, 2022). "Hence, the further study of NFATc4 function in various cancers could help to prevent the precancerous development and improve the individualized cancer therapy." (PMID 35698138, 2022). "The reports implied that NFATc4 is as essential as other NFAT proteins in its role in diseases, particularly cancer." (PMID 39822413, 2024). "We identified several TFs, including GTF2I, NFIB, NFATC4, ZNF37A, KLF13, and ZNF507, involved in cancer metastasis." (PMID 39273015, 2024). "Recent reports also suggest that NFATc4 and NFAT5, which have not previously been extensively associated with cancer, showed otherwise." (PMID 39822413, 2024). "The significant DMR for NFATC4, located on an intron, had 15% hypermethylation between obese and non-obese cancer, and NFATC4 had a marginal interaction with age in the GR model." (PMID 35629083, 2022). "Interestingly, reactivation of MYC, following the upregulation of NFATC4, partially inhibited the quiescent phenotype and failed to fully restore proliferative phenotype in cancer cells." (PMID 38418814, 2024).
infection (2 papers, 2013 to 2018). The state of being infected such as from the introduction of a foreign agent such as serum, vaccine, antigenic substance or organism. "While IRF4 and STAT6 had similarly elevated expressions at 2, 4, 8 and 12 weeks, JAK1 and NFATC4 were upregulated at comparable levels from 2 to 8 weeks and then downregulated at 12 weeks post-infection." (PMID 23448601, 2013). "In addition, except for 4 of the regulatory genes (IRF4, JAK1, NFATC4 and STAT6), many of the other genes in this pathway were only transiently expressed at 2 (IL4R and PTPRC) or 4 and/or 8 (IL13, IL4 and CEBPB) weeks post-infection." (PMID 23448601, 2013).
cardiovascular disease (1 paper, 2023). "NFAT protein family is the main substrate of CaN and includes NFAT1 (NFATc2), NFAT2 (NFATc1), NFAT3 (NFATc4), NFAT4 (NFATc3) and NFAT5, among which NFATc3 protein is highly related to the development of cardiovascular disease." (PMID 37735624, 2023).
retinopathies (1 paper, 2015). "Together, these studies show a clear role for NFAT-signaling in TNFα-induced retinal leukostasis, and identify NFATc2 and NFATc4 as potentially valuable therapeutic targets for treating retinopathies in which TNFα plays a pathogenic role." (PMID 26527057, 2015).
NFATC4 also shares sentences with these, for which no sentence is quoted: acute myelocytic leukemia (2 papers); breast tumor (2); hypertrophy (2); mental dysfunctions (2); osteoarthritis (2); triple-negative breast carcinoma (2); Ventricular hypertrophy (2); adenovirus infection (1); aortic valve disease (1); Bicuspid aortic valve (1); Brachycephaly (1); C. perfringen infection (1); cystic kidneys (1); diabetes (1); endometrial cancer (1); epilepsy (1); gastric cancer (1); Hypertension (1); long QT syndrome 1 (1); Luminal Breast Cancers (1); lung adenocarcinoma (1); lung squamous cell carcinoma (1); medulloblastoma (1); mitral valve disease (1); myelofibrosis (1); neuroblastoma (1); primary aldosteronism (1); primary myelofibrosis (1); prostate carcinoma (1); renal fibrosis (1).
A further 4 diseases each share a sentence with NFATC4 in 1 paper.